INS (insulin)
Diseases named in the same sentence as INS in open-access papers (continued):
Sharing a sentence is not in itself a finding about the gene and the disease.
Insulin resistance (continued). "They demonstrated that only miR-18a-5p was upregulated in children belonging to the overweight or obese groups, while miR-146-5p, miR-423-3p and miR-152-3p were found to be associated with insulin resistance irrespective of their insulin sensitivity." (PMID 40302954, 2024). "Moreover, this expression was positively correlated with insulin concentrations in plasma collected from fasting individuals, suggesting the involvement of TNF-α in insulin resistance, which is frequently associated with obesity." (PMID 39275140, 2024). "T2DM is a heterogeneous, multifactorial, polygenic disease that may be characterized by a defect in insulin secretion (the beta cell secretory defect), insulin action (insulin resistance), and chronic hyperglycemia." (PMID 38255202, 2024). "These alterations may be related to the catecholamine-induced insulin resistance or insulin suppression." (PMID 38849646, 2024). "However, they can also lead to insulin resistance and impaired insulin secretion, eventually resulting in PTDM." (PMID 38337487, 2024). "Insulin resistance is defined clinically as an individual's inability to increase glucose uptake and utilization as much as a normal individual with an equivalent amount of exogenous or endogenous insulin." (PMID 39628749, 2024). "cascavella can promote insulin secretion in pancreatic β-cells during insulin resistance (IR)." (PMID 39398348, 2024). "Additionally, increasing BMI and arising insulin and insulin resistance levels represent other cofactors." (PMID 38785834, 2024). "Importantly, pharmacological interventions such as metformin, and supplementation with inositol, both insulin-sensitizing agents, have been shown to improve insulin sensitivity and reduce insulin resistance in PCOS." (PMID 39276209, 2024). "Furthermore, blocking the PI3K pathway disrupts insulin signaling which can have a significant impact on insulin resistance." (PMID 39410536, 2024). "Six weeks of essential oil treatment reduced time in the positive phase (treatment*covariate p = 0.04) and insulin concentrations at 75 min (treatment*covariate p = 0.0008), two markers of insulin sensitivity, in horses with severe initially degree of insulin resistance." (PMID 39687851, 2024). "Moreover, acute insulin resistance results in decreased glucose uptake due to impaired post-receptor insulin signaling and the downregulation of GLUT-4." (PMID 39682557, 2024). "DM results either from insulin resistance or defect in insulin production." (PMID 38331889, 2024). "In older individuals, cerebral insulin resistance may partly be due to impaired insulin transport into the CNS, affecting brain neuronal function." (PMID 38534454, 2024). "In a retrospective study of children aged 2–18 years, TSH concentrations showed a positive correlation with BMI, triglyceride concentrations, fasting insulin, and insulin resistance as assessed by the Homeostasis Model Assessment for Insulin Resistance (HOMA-IR) index." (PMID 39203787, 2024). "As central obesity is a major component of metabolic syndrome, it is not surprising that acne patients may frequently exhibit increased levels of serum glucose and insulin as well as insulin resistance." (PMID 38883100, 2024). "T2D is mostly caused by insulin resistance and is distinguished by the absence of pathological alterations in the pancreas and insensitivity of other body parts and tissues to insulin." (PMID 39568808, 2024). "However, in studies using the hyperinsulinaemic–euglycaemic clamp, the gold standard for assessing insulin action in vivo, insulin resistance is evident in participants with type 1 diabetes, involving both central and peripheral tissues." (PMID 37914981, 2024). "Furthermore, human KST ameliorates diet-induced hepatic insulin resistance in mice, while differentially affecting skeletal muscle and adipose tissue insulin sensitivity." (PMID 38431218, 2024).
Insulin resistance (continued). "However, the total cholesterol, insulin, and insulin resistance levels were greater than those in the wild type." (PMID 38674326, 2024). "Additionally, nebivolol has been shown to improve insulin resistance related variables, fasting glucose, fasting insulin, and the homeostatic model assessment of insulin resistance (HOMA-IR)." (PMID 39759452, 2024). "Indeed, in patients with T2DM or insulin resistance, high insulin levels are related to the dysregulation of intestinal lipoprotein metabolism." (PMID 38668314, 2024). "Thus, by these means, TNF-α accumulation impedes cellular insulin signaling and can eventually result in insulin resistance." (PMID 39201652, 2024). "Both types manifest with sustained hyperglycemia, however, T1DM is caused by autoimmune injury to pancreatic beta cells producing insulin, while T2DM develops due to insulin resistance caused by different metabolic risk factors such as obesity and dyslipidemia." (PMID 39598447, 2024). "Likewise, glucosyltransferase enzyme inhibitors also increase insulin sensitivity and glucose tolerance in murine models of insulin resistance and obesity." (PMID 39408263, 2024). "None of the MUO-associated parameters tested (BMI, waist circumference (WC), SBP, DBP, fasting TAG, HDL-C, glucose, insulin, and homeostasis model assessment of insulin resistance (HOMA-IR)) showed any significant correlation with oGRS (after the test correction)." (PMID 36982283, 2023). "DM is a chronic disease with two different forms depending on whether there is insulin resistance or poor insulin secretion." (PMID 38022061, 2023). "Furthermore, plasma level of ZAG was negatively correlated with insulin and the homeostasis model assessment for insulin resistance index (HOMA-IR)." (PMID 37830580, 2023). "In addition, inflammatory cytokines (tumor necrosis factor-alpha and interleukin-6) released by macrophages accumulated in visceral adipose tissue can weaken insulin sensitivity and thus promote insulin resistance." (PMID 37674809, 2023). "To investigate whether the increase in insulin secretion led to glial insulin resistance, we used a transgenic line that expresses a fluorescent reporter (tGPH) for Pi3k, a downstream effector of IR signaling." (PMID 37934726, 2023). "IL-6 may be also involved in the pathogenesis of hepatic insulin resistance as insulin sensitivity increases in diet-induced obese mice treated with anti-IL-6 antibodies." (PMID 37999226, 2023). "Insulin level and homeostasis model assessment of insulin resistance (HOMA-IR) before treatment corresponded to values of hyperinsulinemia (>109 pmol/L) and insulin resistance (IR) (>2.5); after weight-loss intervention, a significant decrease in these indicators was noted." (PMID 37686231, 2023). "A drug usually used to treat high blood pressure (hypertension) shows great promise in preventing insulin resistance, where cells no longer respond to insulin thereby increasing the risk of type 2 diabetes, by reducing intracellular calcium overload in cells." (PMID 37121975, 2023). "At certain doses, biochanin-A reduced glucose tolerance and insulin resistance, developed insulin sensitivity and increased SIRT-1 expression which might explain the anti-diabetic properties of the drug." (PMID 38106650, 2023). "Furthermore, insulin resistance can lead to dysregulation of insulin signaling pathways within the brain." (PMID 38002034, 2023). "Metabolic diseases such as obesity and its severe complication, type 2 diabetes, are associated with insulin resistance where the AKT signaling pathway is impaired, leading to abnormal glucose metabolism in insulin-responsive tissues including BAT, WAT, and skeletal muscles." (PMID 37126544, 2023). "Thus, excessive nicotine intake produced by insulin resistance is likely modulated via insulin modulation of dopamine transmission." (PMID 38389818, 2023).
Insulin resistance (continued). "Insulin resistance in T2DM is associated with both hyperglycemia and hyperlipidemia, which are associated with an imbalance between endocrine pancreatic function and hepatic and extrahepatic insulin sensitivity." (PMID 36747287, 2023). "In addition, melatonin can help restore the function of islet B cells, improve insulin sensitivity and glucose tolerance, reduce hyperinsulinemia, and reduce insulin resistance." (PMID 36348200, 2023). "Peripheral insulin resistance and the compensatory hypersecretion of insulin from pancreatic islets may precede a decline in islet secretory function in this form of the disease." (PMID 37759802, 2023). "Both insulin resistance and impaired insulin secretion are hallmarks of T2D." (PMID 37795366, 2023). "MAFLD, coexisting with insulin resistance and inflamed adipose tissue is responsible for a plasma environment conducive to atherosclerosis, with increased concentrations of triglycerides, glucose and insulin." (PMID 37999226, 2023). "While control cells exhibited a greater proportion of increased protein phosphorylation than decreased phosphorylation (1402 increased phosphopeptides, 459 decreased phosphopeptides), insulin-regulated dephosphorylation was preferentially impaired in insulin resistance." (PMID 36808134, 2023). "In turn, adiponectin increases insulin sensitivity, decreasing insulin resistance." (PMID 36675592, 2023). "O. aristatus is reported to have α-amylase and β-glucosidase inhibitory activities, exhibits antioxidant and anti-inflammatory properties, regulates lipid metabolism, promotes insulin secretion, improves insulin resistance, increases glucose uptake, promotes glycolysis and inhibits gluconeogenesis." (PMID 36678606, 2023). "A large body of evidence suggests that inflammatory cytokines such as TNF-α, IL-1β, and IL-6 not only induce systemic insulin resistance but also affect lipid metabolism, whereas the presence of IL-10 effectively improves insulin sensitivity and HFD-induced obesity." (PMID 38162665, 2023). "The finding that a disruption in insulin systems increases nicotine reward is consistent with a prior report showing that a subthreshold dose of nicotine only produced CPP in a sub-set of HFD-fed rats that also displayed insulin resistance." (PMID 38389818, 2023). "Puberty is characterized by increased insulin resistance, which might explain the increase in weight-related basal insulin." (PMID 40303252, 2023). "Several molecular pathways could contribute to the decrease in insulin resistance following AT, including the upregulation of insulin-responsive transporters and insulin signal transduction." (PMID 37689713, 2023). "What is more, insulin level reduction was also observed, which could suggest insulin resistance reduction." (PMID 36983908, 2023). "Chronically high insulin levels can further lead to insulin resistance." (PMID 36804018, 2023). "The effects of volatile anesthetics on basal insulin secretion and hepatic insulin extraction, an indicator of insulin resistance, are unknown." (PMID 36808704, 2023). "This leads to increase of insulin resistance and decreased in the effectiveness of insulin." (PMID 37692463, 2023). "In addition, they suffered from a significant increase in four indices of non-insulin-based insulin resistance." (PMID 36846644, 2023). "In addition, we identified cut-off values for leptin in the assessment of obesity and insulin in the assessment of insulin resistance in patients with abnormal body weight." (PMID 37373485, 2023). "Increase in branch-chain amino acids (BCAAs) and phenylalanine may attenuate insulin sensitivity and enhance insulin resistance." (PMID 37492592, 2023). "Therefore, PTP1B is a key regulator of the insulin signaling pathway, and its overexpression, or unusual activation, contributes to the onset of insulin resistance." (PMID 36839851, 2023).
Insulin resistance (continued). "Moreover a true fasting state was probably not really achieved in many subjects, leading to elevated glucose and insulin concentrations at baseline and thereby to inflated insulin resistance by the homeostatic model assessment." (PMID 36771243, 2023). "Moreover, in previous studies, baseline insulin resistance and recovery of insulin sensitivity after SIIT were also considered vital factors for glycemic remission." (PMID 36650669, 2023). "By contrast, higher insulin levels could enhance liver Cd36 expression and induce steatosis and hepatic insulin resistance." (PMID 37852177, 2023). "Besides, enhanced hepatic glucogenesis with the progression of pregnancy, along with a concurrent increase in insulin resistance, leads to a physiological surge in insulin secretion." (PMID 37942393, 2023). "Moreover, insulin resistance reflected by Akt phosphorylation in our study was conducted within 5 min after exogenous insulin infusion through the vena cava." (PMID 36835312, 2023). "To obtain independent validation of some of the candidates revealed from CMAP, we performed a screen for compounds that affect GLUT4 translocation to the cell surface in L6 myotubes expressing HA-tagged GLUT4 (GLUT4-HA-L6), a readout of insulin action that is defective in insulin resistance." (PMID 37494090, 2023). "A potential sign that may assist in determining readiness for feeding may be the degree of insulin resistance, as can be derived from the amount of insulin required to maintain blood glucose at a predefined level." (PMID 36707883, 2023). "Insulin resistance refers to a decrease in the metabolic response of target cells to insulin." (PMID 38179301, 2023). "IRS-1 regulation differs in the liver as it has been observed in diabetic animals, which may result in distinctive changes in insulin levels in liver tissue and contribute to insulin resistance in liver." (PMID 37089941, 2023). "Impaired insulin signaling pathways and insulin resistance are the second main adjustments." (PMID 37893045, 2023). "Women with RPL have high fasting insulin and insulin resistance." (PMID 36604717, 2023). "A period of 12 weeks on a hypocaloric diet with 30 mg per day of elemental zinc supplementation, at the endpoint, resulted in a decrease in insulin resistance and improvement of the insulin serum superoxide dismutase 1 and malondialdehyde levels in overweight NAFLD-diagnosed patients." (PMID 36902639, 2023). "Similarly, rosemary extract and diterpenes including CA and CAR were shown to increase insulin sensitivity, alleviate insulin resistance and protect cells from high-glucose-induced damage both in vitro and in vivo." (PMID 36831081, 2023). "In the early stages of the development of insulin resistance, the pancreas can compensate for this by increasing insulin secretion into the bloodstream in an attempt to overcome defects in the peripheral action of insulin." (PMID 37239168, 2023). "Since physical training in T2DM results in the increased translocation of muscle GLUT4 transporters and increased capacity for insulin-stimulated glucose uptake, as well as reduced insulin resistance, physical activity is an important intervention against T2DM." (PMID 37627482, 2023). "Under the long-term stimulation of high concentrations of leptin, the receptor responsiveness of the islets β cells of the body decreased, thereby reducing the inhibitory effect of leptin on insulin synthesis and increasing insulin secretion, leading to hyperinsulinemia and insulin resistance." (PMID 37560059, 2023). "Interestingly, the MPs group further significantly increased blood glucose levels, the AUC of glucose in an OGTT, and fasting insulin levels, and worsened insulin resistance in comparison to the HFD group (p < 0.01)." (PMID 37569796, 2023).
Insulin resistance (continued). "The etiology and pathogenesis of DM2 comprise genetic predisposition, obesity, sleep time deficit or excess, as well as other factors associated with development of insulin resistance and impaired insulin response to glucose or non-glucose stimuli." (PMID 37790608, 2023). "It has been proposed that excessive amounts of AAs may reduce insulin-stimulated glucose uptake and increase insulin resistance." (PMID 37798798, 2023). "Measurement of in vivo hepatic insulin signaling indicated that the acute knockdown of hepatic DG acyltransferase-2 increases the accumulation of DG, which in turn activates PKCε and induces insulin resistance in the liver." (PMID 37124226, 2023). "Insulin resistance may also occur in hypothyroidism, where there is a reduction in glucose-induced insulin secretion by β cells." (PMID 37627914, 2023). "Analyses restricted to non-Hispanic Black participants had the same direction of effect as European-ancestry individuals for three of the cluster pPS: Preserved Insulin Secretion Cluster, Insulin Resistance-Lipodystrophy Cluster, and Elevated Insulin Secretion Cluster." (PMID 37790568, 2023). "MiR-16 has been found to impact insulin resistance and inhibit cell apoptosis induced by hyperglycemia, by targeting genes involved in biological processes such as insulin signaling, insulin receptor substrate (IRS) proteins 1 and 2, and insulin-like growth factor-I (IGF-I)." (PMID 37330548, 2023). "In earlier reports, statins therapy increased the risk of new-onset diabetes, which was speculated to reduce insulin production or increase insulin resistance and thereby affect glucose homeostasis." (PMID 37206443, 2023). "In human samples, the interface could reliably detect a range of insulin concentrations corresponding to individuals’ insulin resistance and timing of food intake." (PMID 37258547, 2023). "Excessive activation of MR in ECs leads to vascular insulin resistance, which refers to the impaired responsiveness of blood vessels to the actions of insulin and related reduction in insulin-mediated capillary recruitment, glucose delivery, and subsequent tissue glucose uptake." (PMID 37610001, 2023). "Moreover, an improved glycemic index alleviates relevant parameters, including OGTT, fasting insulin levels, and insulin resistance in HOMA-IR." (PMID 37040355, 2023). "The interaction between T2D type and fracture risk also needs exploration, as factors such as body weight, insulin, insulin resistance, and metabolic control could potentially modify fracture risk." (PMID 38025038, 2023). "Therefore, we measured four different non-insulin-based insulin resistance indexes: TyG, TyG-BMI, TG/HDL-C, and METS-IR." (PMID 36846644, 2023). "Insulin resistance by inhibiting insulin activates the P13K-AKT pathways that inhibit granulosa cell lactic acid; lactic acid, as the main granulosa cells to supply oocytes’ generation energy substrate, meet the energy needs of oocyte development, resulting in oocyte energy supply." (PMID 38003436, 2023). "SARS-CoV-2 penetrates cells via the ACE2 pathway, and as ACE2 is extensively expressed in the liver and pancreas, it may have a role in insulin resistance and decreased insulin production." (PMID 36984473, 2023). "Also, alternative markers of insulin resistance have been introduced to predict the risk of T2DM such as lipoprotein particles’ concentration and size, glucose, and insulin levels." (PMID 37434259, 2023). "The LBW individuals with NAFLD were characterized by elevated hepatic insulin resistance, fasting levels of insulin, C-peptide, and triglycerides (TG), as well as elevated plasma levels of leptin and GLP-1, compared with both LBW and normal-birth-weight (NBW) individuals without NAFLD." (PMID 37049431, 2023).